SOCS3 (suppressor of cytokine signaling 3)
Diseases named in the same sentence as SOCS3 in open-access papers (continued):
Sharing a sentence is not in itself a finding about the gene and the disease.
tumor (300 papers, 2003 to 2026). "Multiple studies have shown that reduced SOCS3 expression is associated with tumor development and progression, including NSCLC." (PMID 41567211, 2025). "SOCS1 expression in macrophages is associated with a more aggressive tumor phenotype, while SOCS3 correlates with an anti-tumor response." (PMID 41230456, 2025). "This SOCS3 deficiency in macrophages was associated with a significant reduction in M2-polarized tumor-associated macrophage (TAM) infiltration into neoplastic tissues." (PMID 40838069, 2025). "According to the Cox proportional hazards regression model, the SOCS3 expression was less obviously associated with prognosis and tumor progression." (PMID 37025997, 2023). "SOCS1 and SOCS3 were important negative regulators of tumor-associated immune cells during tumor development, PE inhibited the activation of JAK2 in SOCS1." (PMID 37355637, 2023). "SOCS3 is erased or epigenetically downregulated in solid tumors, and functional deficiency has been implicated in tumor progression and metastasis." (PMID 37081748, 2023). "IL-9 mRNA levels in tumours showed a marked correlation with the Th9-associated transcription factors Irf4, Gata3, and Spi1, as well as with Socs3." (PMID 35793807, 2022). "Loss of SOCS3 expression is associated with cancer-associated inflammation and immunity suppression, favouring tumour growth and metastasis." (PMID 35267409, 2022). "Berger and colleagues identified activation of suppressor of cytokine signaling 3 (SOCS3) by PPARγ agonists as another pathway implicated in suppression of tumor angiogenesis and growth." (PMID 32785018, 2020). "SOCS1 and SOCS3 have been associated with tumour progression and response to treatments in different kinds of cancers, including GBM." (PMID 30811476, 2019). "Higher mRNA expression levels of SOCS3 are significantly associated with earlier tumor stage and better clinical outcome in human breast cancer." (PMID 30787278, 2019). "In line with this evidence, expression of representative IL-6-mediated STAT3 target genes such as Socs3 and Timp1 were largely unaltered in tumor livers of lean IL-6Rα-deficient mice compared to controls." (PMID 30224299, 2018). "SOCS-1, SOCS-3 inhibiting JAKs and regulating tumor-associated inflammation, then inhibit a variety of tumor development and invasion." (PMID 30788302, 2018). "A previous study reported that NDRG2 can inhibit IL-10 expression, which plays an important role in tumor-associated immune response by modulating SOCS3 and STAT332." (PMID 29445150, 2018). "Our data demonstrate that the hypermethylation status in the SOCS3 promoter is associated with downregulation of the SOCS3 mRNA expression in tumor tissues." (PMID 28179578, 2017). "In this study, we focused on IL-22 signaling and identified SOCS3 protein, an intracellular inhibitor of cytokine-associated signaling, as a valid candidate to suppress tumor responses of BCC and SCC." (PMID 28445952, 2017). "SOCS3 promoter hypermethylation was associated with relatively low mRNA expression in tumor tissues (P=0.0023)." (PMID 28179578, 2017). "The aberrant methylation of the CpG islands in the SOCS3 promoter is associated with relatively low mRNA expression in tumor tissues." (PMID 28179578, 2017). "Our data thus far indicate that loss of SOCS3 in macrophages results in an enhanced M1, or pro-inflammatory, anti-tumor phenotype when exposed to GCM." (PMID 26967393, 2016). "Only A20 showed a statistically significant association with the TNM stage, while SOCS3 merely showed a significant association with tumor differentiation." (PMID 26485275, 2015). "Despite upregulation of typical M2 markers (arginase I and IL-10), usually associated with tumor progression, SOCS3-deficient macrophages provided tumor protection because of enhanced MCP-2/CCL8 production." (PMID 26579124, 2015). "IEC-specific silencing of SOCS3 leads to a dramatic increase in tumor load in a mouse model of inflammation-associated CRC." (PMID 20500855, 2010).
tumor (continued). "Conversely, excessive Stat3 activation, through epithelial-specific Socs3 ablation or introduction of the Socs3-binding deficient gp130Y757F mutation, results in increased tumour burden both in terms of tumour size as well as incidence." (PMID 20478049, 2010). "The expression of SOCS3 is decreased due to aberrant methylation, and its transcriptional silencing is associated with malignant tumor behaviors." (PMID 18507841, 2008). "While we have previously observed that SOCS3 secretion by AMs is diminished in tumor-bearing lungs, the mechanisms underlying this impairment remain unclear." (PMID 41567211, 2025). "The results suggested that SOCS3 might be associated with macrophage infiltration and tumor invasion in lung metastasis." (PMID 37025997, 2023). "We used various computational tools to explore the expression and pathogenic roles of SOCS3 in several types of cancer, assessing its potential role in the pathogenesis of cancer, in tumor immune infiltration, tumor progression, immune evasion, therapeutic response, and prognostic." (PMID 35600392, 2022). "SOCS3 hypermethylation was also associated with high levels of Treg cells, which impede intrinsic anti-tumor immunological functions and decrease the clearance of residual tumor cells leading to an increased risk of relapse." (PMID 34439155, 2021). "Moreover, we found that the downregulation of SOCS3 was significantly associated with the aggressive phenotypes of tumors (p < 0.001) and tumor size (p = 0.027)." (PMID 34691358, 2021). "Low expression of SOCS3 was associated with TNM stage and tumor size, suggesting that SOCS3 may influence OS." (PMID 34691358, 2021). "Moreover, this study indicated that loss of SOCS3 decreased tumor formation when compared to control mice." (PMID 34646310, 2021). "Similar approaches may be considered to the combination of PTEN, SOCS3, and c-Myc, which leads to a robust axon growth but are also associated with tumor formation." (PMID 28824380, 2017). "However, it has also been reported that SOCS3 deficiency in myeloid cells promotes tumor development by inducing MDSCs in the tumor microenvironment." (PMID 29326716, 2017). "The SOCS3−/− mice also exhibited reduced tumor incidence, indicating that the loss of SOCS3 in the myeloid cell population may aide in tumor rejection." (PMID 26967393, 2016). "However, only A20 showed a significant association with the tumor node metastasis (TNM) stage, while SOCS3 showed a significant association with tumor differentiation." (PMID 26485275, 2015). "The results of this in vivo study underscore that ascribing M1 macrophages as tumoricidal may be over simplistic, as the SOCS3-deficient macrophages had lower expression of M1 markers and increased M2 markers yet afforded tumor protection." (PMID 26579124, 2015). "As a putative tumor suppressor gene, determination of expression and subcellular localization of SOCS3 may be useful as a diagnostic tool or as a therapeutic target in gene therapy studies." (PMID 23028842, 2012). "This also supports our previous studies that linked the inhibition of SOCS3 packaging to shifts in glycolytic flux and the generation of acetyl-CoA in response to GM-CSF, a growth factor that is itself known to be elevated in tumor-bearing lungs and can promote immune cell evasion by tumor cells." (PMID 41567211, 2025). "SOCS1 and SOCS3 proteins were initially described as onco-suppressors, being silenced in many tumors as consequence of hypermethylation of their promoters or mutations influencing proliferation, differentiation and survival of immune cells controlling tumor expansion." (PMID 38975347, 2024). "Additionally, targeting newer GSC-specific markers, such as the stem-like cell marker SOX2 that promotes tumour progression or SOCS3, USP8, and DOT1L, which were recently linked to GSC growth, may be more efficient." (PMID 38136335, 2023). "However, inhibition of SOCS3 is also implicated in tumor progression and malignancy." (PMID 19698101, 2009).
tumor (continued). "SOCS3 functions as a tumor suppressor in many contexts, where its downregulation correlates with enhanced tumor growth, angiogenesis, and immune evasion." (PMID 40310419, 2025). "In the case of SOCS3, there was a significantly higher immunoexpression level in cancer in comparison to the control (mastopathy vs. tumor: 6.46 ± 2.42 vs. 7.77 ± 2.77, p < 0.001)." (PMID 40003884, 2025). "AMs derived from tumor-bearing lungs exhibited significantly reduced SOCS3 secretion compared to those from non-tumor-bearing lungs." (PMID 41567211, 2025). "Lines of evidence suggest that SOCS3 expression is higher in adjacent tissues compared to BC tumor tissues." (PMID 40003884, 2025). "In conclusion, our findings suggested that FXR exerted a tumor-suppressive effect in HCC by inhibiting the phosphorylation of STAT3 in HCC stem cells through targeting SOCS3." (PMID 39940889, 2025). "Our research showed a similar trend, with a higher SOCS3 mRNA expression in the tumor margin compared to neoplastic tissue." (PMID 40003884, 2025). "In the GBM TME, dysregulated SOCS1 and SOCS3 expression suppress anti-tumor immune responses by impairing CD8+ T cell and NK cell function." (PMID 40076502, 2025). "So far, data have shown associations of SOCS3 with benign tumors and indicate a decrease in SOCS3 levels as the tumor’s stage advances." (PMID 40003884, 2025). "SOCS3 plays a crucial role in the anti-tumor effects of the pathway by promoting cell apoptosis through inhibition of STAT3 phosphorylation and subsequent downstream factors." (PMID 40426998, 2025). "One study’s findings include the significant downregulation of SOCS3 in DRG following tumor cell injection, and subsequent overexpression attenuated pain hypersensitivity probably via reversing TLR4 upregulation." (PMID 38940936, 2024). "Lastly, Socs3 is a negative regulator of NK activity and therapeutic targeting of Socs3 in NK cells potentiates the killing of tumor targets." (PMID 39518148, 2024). "As for SOCS1, aberrant expression of SOCS3 has been observed in certain cancers, influencing the tumor microenvironment and immune responses." (PMID 38975347, 2024). "In 2017, we performed a study aimed at rescuing the decreased SOCS3 activity in these tumor contexts by using a SOCS3-derived KIR-ESS peptide." (PMID 38975347, 2024). "Using CRISPR/Cas9 technology to delete IL30 in PC cells led to the suppression of these oncogenes and the upregulation of the tumor suppressor SOCS3, significantly inhibiting tumor growth and metastasis." (PMID 39125732, 2024). "Lnc-DANCR knockdown prevents EZH2 from binding to the SOCS3 promoter, leading to SOCS3 upregulation, which in turn inhibits tumor growth." (PMID 39830662, 2024). "The relationship between SOCS3 and the AhR was further investigated in AhR deficient mice in the AOM/DSS tumor model where SOCS3 levels were increased in tumors compared to uninvolved mucosa." (PMID 38651159, 2023). "The SOCS3 expression of lung metastasis was significantly higher than in the colon primary tumor, whereas that in liver metastasis was the opposite." (PMID 37025997, 2023). "Taken together, Res inhibited STAT3 signaling through modulation of PIAS3, SHP1, SHP2, and SOCS3, thereby attenuating tumor growth and increasing sensitivity to TMZ." (PMID 37298405, 2023). "Immunostaining of MBM generated by an intra-cardiac inoculation of YDFR.CB3GFP or M12.CB3GFP cells revealed that SOCS3 was expressed in brain stroma and at lower levels in tumor cells." (PMID 37296634, 2023). "Currently, SOCS3 has turned out to involve in the process of embryonic development, inflammatory response, immunoregulation, and tumor progression." (PMID 37025997, 2023).
tumor (continued). "Suppression of SOCS3 in macrophages exerted anti-inflammatory and anti-tumor effects through the hyperactivation of STAT3 in the myeloid cell." (PMID 37025997, 2023). "The pro-tumor activity of IL-10 relied, at least in part, on the over-expression of SOCS-3 (Suppressor of Cytokine Signaling 3) that in turn inhibited the anti-tumoral IL-6 signaling pathway in macrophages co-cultured with metastatic tumor cells." (PMID 37835437, 2023). "To figure out the difference in SOCS3 expression between normal tissue and tumor tissue in different cancer types, we explored the expression data in TCGA and GTEx databases." (PMID 37025997, 2023). "Meanwhile, we will explore the effect of SOCS3 alterations in tumor cells on surrounding macrophage polarization and its role in tumor invasion." (PMID 37025997, 2023). "Altered SOCS3 combined with chemotherapy or targeted therapy has been demonstrated to sensitize tumors and inhibit tumor progression." (PMID 37025997, 2023). "The knockout of SOCS3 also promoted the tumor growth and metastasis in vivo, as evidenced by the increased tumor size and more metastatic lung nodules in animal experiments." (PMID 37270563, 2023). "In the present study, we demonstrated that brain-metastasizing tumor cells uniformly impact the expression of microglial SOCS3." (PMID 37296634, 2023). "As cytokines and growth factors that facilitate physiological hepatocyte proliferation also drive hepatocarcinogenesis, SOCS1 and SOCS3 likely mediate their tumor suppressor functions, at least partly, via attenuating HGF and IL-6 signaling, respectively." (PMID 36765862, 2023). "SOCS3 expression and changes in the tumor-cell immune infiltration were predicted through the presence of immunosuppressive cells (MDSCs, CAFs, M2-TAMS, and Tregs) that promote T-cell exclusion." (PMID 37047482, 2023). "Meanwhile, SOCS3 played different roles in different tumor types, being pro-oncogenic or tumor suppressive." (PMID 37025997, 2023). "Tocilizumab has been proposed to support the anti-tumor effect of IFNα treatment in RCCs by inhibiting the IL-6-mediated expression of the suppressor of cytokine signaling 3 (SOCS3)." (PMID 37190141, 2023). "Compared with adjacent normal intestinal mucosal tissue, SOCS3 status in colon primary tumor tissue was slightly weak, mainly with moderate positive staining in the cytoplasm." (PMID 37025997, 2023). "Subsequently, DEGs were compared between low SOCS3 expression and high SOCS3 expression in colon primary tumor and lung metastasis with |log2FC| > 1 and p < 0.05." (PMID 37025997, 2023). "In lung cancer, SOCS3 inhibited tumor cell proliferation and angiogenesis in small-cell lung cancer cells via inhibiting HIF-1α and promoted apoptosis and cell proliferation in non-small-cell lung cancer through its methylation." (PMID 37025997, 2023). "To shed further light on the potential function of SOCS3 in pan-cancer, we divided patients into low and high expression groups in each tumor according to median levels of SOCS3 expression, and performed DEGs analysis." (PMID 37025997, 2023). "SOCS3 silences the expression of its downstream gene, C-myc, and reduces the possibility of tumor occurrence." (PMID 35558081, 2022). "In the meanwhile, we also performed IHC staining of cell proliferation marker Ki-67 and SOCS3 in tumor sections." (PMID 35818076, 2022). "Among the most downregulated miRs post‐PH, we found 4 miRs (miR‐106a‐5p, miR 340‐5p, miR‐19b‐3p and miRNA‐455‐5p), targeting Socs3, a known tumour suppressor and an inhibitor of cell cycle." (PMID 35174557, 2022). "We discovered that the expression of SOCS3 was positively relevant to tumor infiltration of MSDCs in CESC, KIRC, and SKCM-Primary, whereas it was negatively correlated with BRCA-LumA, COAD, KICH PAAD, PCPG, PRAD, STAD, and THCA." (PMID 35600392, 2022).
tumor (continued). "In contrast, SOCS3, which has been shown to be increased in DCs by tumor-derived substances, interacts with PKM2, resulting in decreased ATP generation under hypoxic conditions and a profound effect on the function of DCs." (PMID 36311734, 2022). "In this study, we first detected the differential expression of SOCS3 in cancer tissues and para-cancerous tissues, and then detected the expression level of miR-92a in tumor cell lines." (PMID 35184640, 2022). "SOCS3 gene is a tumor suppressor that plays a role in the regulation of various signaling pathways and immune molecules, thereby preventing malignant proliferation, invasion, and metastasis." (PMID 35558081, 2022). "SOCS3 expression levels were also found to be significantly lower in PCa cell lines and PCa tumor tissues." (PMID 35818076, 2022). "Intriguingly, in IL30 knockout tumor xenografts, overexpression of SOCS3 also involves infiltrating macrophage-like cells, suggesting that the effects of IL30 gene deletion in PC cells span to the surrounding immune cells." (PMID 36224639, 2022). "Our data support the tumor-suppressor function of SOCS3 and highlights the role of SOCS3/JAK2/STAT3 axis in PCa progression." (PMID 35818076, 2022). "The SOCS3 expression level was negatively correlated with CTL in some tumor patients, suggesting interactions with T-cell exclusion." (PMID 35600392, 2022). "Deletion of IL30 dramatically downregulated BCL2, NFKB1, STAT3, IGF1 and CXCL5, whereas tumor suppressors, primarily SOCS3, were upregulated." (PMID 36224639, 2022). "We demonstrated that the expression of both STAT3 and SOCS3 was up-regulated in DMS114 tumor cells pre-incubated with the tumor-activated SC-conditioned medium." (PMID 36551618, 2022). "ANKRD13B, ISG15, KBTBD12, KLHL35, and UHRF1 were upregulated in tumor samples; DCUN1D5, HCK, and SOCS3 were downregulated in tumor than in normal samples." (PMID 35884544, 2022). "Alterations in SOCS3 expression and tumor cell immune infiltration were also predicted by the presence of immunosuppressive cells (MDSCs, CAFs, M2-TAMS, and Treg), which promote T-cell exclusion." (PMID 35600392, 2022). "The results from a third-generation HSV oncolytic suppressor of cytokine signaling 3 (SOCS3) showed an increase in proliferation and tumor cell lysis properties for the MKN1 cell line as well as in human GC specimens." (PMID 35455349, 2022). "The carcinogenesis was increased in Socs3 h-KO mice, suggesting the essential role of SOCS3 as a tumor suppressor." (PMID 35892823, 2022). "We observed high expression of miR-650 and decreased expression of SOCS3, animportant tumor suppressor, in B[a]P-treated 7404 cells." (PMID 34450627, 2021). "All these data indicate thatmiR-650 promotes tumor cell motility by mediating SOCS3/JAK/STAT3 signalingactivation." (PMID 34450627, 2021). "Results showed significant upregulated expression of certain genes like Hgf, Hmga1, Rasgrp1, Sh2b2, Socs1, Socs2, and Socs3 in WT mice tumor compared to its ChREBP systemic knockout tumor." (PMID 34685767, 2021). "Ad-SOCS3 revealed synergistic antitumor effects, if combined with NK cells in a DU-145 xenograft tumor model." (PMID 34830179, 2021). "Conversely, expression of the genes associated with NK cell exhaustion, such as PDCD1, CTLA4, KLRC1, NR4A1, and SOCS3, was upregulated in tumor-infiltrating NK cells." (PMID 34535671, 2021). "In the Ivy-GAP dataset, we identified eight patients treated with BVZ who also had RNA-Seq data of SOCS3 expression at anatomical locations of a cellular tumor." (PMID 33804433, 2021). "Two studies reporting significantly increased expression and 10 reporting significantly decreased expression in tumor tissues were identified for SOCS3." (PMID 34120621, 2021). "Regarding SOCS3 expression, 428 studies were considered, among which 30 showed increased expression and 42 showed decreased expression in tumor tissues compared with normal tissues." (PMID 34120621, 2021).